SATB2 (SATB homeobox 2)
Diseases named in the same sentence as SATB2 in open-access papers (continued):
Sharing a sentence is not in itself a finding about the gene and the disease.
osteosarcoma (23 papers, 2016 to 2026). A usually aggressive malignant bone-forming mesenchymal neoplasm, predominantly affecting adolescents and young adults. "The SATB2 immunohistochemical marker has been shown to help distinguish osteosarcomas of long bones, including the small-cell variant, from their malignant bone tumor mimickers, such as Ewing sarcomas." (PMID 35049602, 2021). "Biopsy revealed malignant osteoid-forming cells with SATB2 positivity, confirming the diagnosis of primary sternal osteosarcoma." (PMID 42254154, 2026). "The neuroblastoma tumouroids demonstrated diffuse strong nuclear PHOX2B staining, Ewing sarcoma tumouroids showed circumferential membrane staining for CD99, and osteosarcoma tumouroids with nuclear SATB2 staining." (PMID 41034452, 2025). "Special AT-rich sequence-binding protein 2 (SATB2) is commonly expressed in osteosarcoma tissues and widely recognized as a definitive marker in the pathological diagnosis of osteosarcoma cell nature." (PMID 38769167, 2024). "On IHC, no expression of H3G34W (normally related to GCTB), H3K36M (chondroblastoma), or SATB2 (osteosarcoma with giant cells) was seen." (PMID 36409159, 2023). "Negative immunoreaction with epithelial markers and positive immunoreaction with SATB2 and low Ki-67 labeling index suggested the diagnosis of osteosarcoma." (PMID 36425109, 2022). "Another study by Connor and Hornick reported SATB2 positivity in all extragnathic osteosarcomas, fibrous dysplasias, and benign bone-forming tumors, such as osteoblastomas and osteoid osteomas." (PMID 35049602, 2021). "Some osteosarcomas can be accurately classified based on expression of one particular sensitive biomarker, SATB2." (PMID 33176814, 2020). "Reduction of SATB2 or N-cadherin resulted in NF-κB inactivation, which led to impaired osteosarcoma sphere formation and tumor cell proliferation." (PMID 31395078, 2019). "SATB2 is involved in the progression of breast cancer, head and neck squamous cell carcinomas, and osteosarcoma." (PMID 31488089, 2019). "Accordingly, the presence of SATB2 in the rhabdoid-appearing cells in our specimen helps to confirm the diagnosis of an osteosarcoma with prominent rhabdoid features." (PMID 28058126, 2016). "This may help to discover targeting proteins for metastatic osteosarcoma and other cancers with high expression of SATB2." (PMID 37274282, 2023). "Previous osteosarcoma studies have shown that targeting SATB2-mediated EMT could inhibit OS cell growth and metastasis." (PMID 37870753, 2023). "Interestingly, metformin reduces SATB2‐mediated osteosarcoma stem cell‐like phenotype and tumour growth through inhibition of N‐cadherin/NF‐kB signalling pathway." (PMID 32885593, 2020). "SATB2 is a transcriptional regulator that plays an important role in osteoblastic differentiation; it is positive in most benign and malignant tumors with osteoblastic differentiation, such as osteosarcomas, osteoblastomas, osteoid osteomas, and fibrous dysplasias." (PMID 41321186, 2025). "In cancers such as osteosarcoma, hepatocellular carcinoma (HCC), head and neck squamous cell carcinoma (HNSCC), or breast cancer, SATB2 expression levels have been observed to be higher than in normal tissues and associated with a poor prognosis." (PMID 40076993, 2025). "Another study of 60 gynecological carcinosarcomas showed SATB2 expression in the foci of osteosarcoma; however, it was also positive in 60% of cases lacking osteosarcoma, mostly in the undifferentiated foci." (PMID 41321186, 2025). "It is evident that SATB2-mediated invasion may be due to interference with LIMA1 expression, which is a key mediator of SATB2-regulated osteosarcoma invasion." (PMID 37274282, 2023). "Although not specific for osteosarcoma, SATB2, a marker of osteoblastic differentiation, is a useful adjunct in distinguishing between hyalinized collagen and osteoid." (PMID 35252051, 2022).
osteosarcoma (continued). "Although SATB2 is a sensitive marker of osteoblastic osteosarcomas, it is not a specific marker and can be seen in adenocarcinomas, especially of colonic origin." (PMID 27738541, 2016). "Elevated expression of SATB2 has been shown to promote EMT in HCC cells, induce the transformation of normal human breast mammary epithelial cells into progenitor-like cells resulting in a malignant phenotype, and to enhance chemoresistance of HNSCC and migration and invasion in osteosarcoma." (PMID 40076993, 2025). "However, the results obtained by Davis and Horvai suggested that SATB2 positivity is not specific for osteosarcoma compared with other primary bone sarcomas." (PMID 33176814, 2020). "However, SATB2 positivity is not specific for osteosarcoma and cannot differentiate it from other primary bone sarcomas, which has been well documented by Davis and Horvai." (PMID 33176814, 2020). "When not found, H3G34W, H3k36M and SATB2 can be examined to identify GCTB, chondroblastoma and osteosarcoma, respectively." (PMID 36409159, 2023).
Intellectual disability (22 papers, 2009 to 2026). "SATB2-associated syndrome is characterized by severe intellectual disability, neurodevelopmental disorders, cleft palate, and dental abnormalities." (PMID 40693189, 2025). "Mutations in SATB2 are linked to SATB2-associated syndromes characterized by intellectual disability, developmental delays, and craniofacial and dental abnormalities." (PMID 39941150, 2025). "Individuals with pathogenic variants in SATB2 display intellectual disability, speech and behavioral disorders, dental abnormalities and often features of Pierre Robin sequence." (PMID 35241104, 2022). "SATB2 haploinsufficiency causes SATB2‐associated syndrome, an autosomal dominant genetic disorder characterized by severe developmental delay, intellectual disability, and craniofacial and dental abnormalities." (PMID 33319920, 2021). "In facts, SATB2 inactivating mutations in humans have been associated with cleft palate, intellectual disability, facial dysmorphism, and development of odontomas, defining a neurocristopathy referred to as SATB2-associated syndrome." (PMID 33527896, 2021). "Satb2-associated syndrome, caused by the alteration in the Satb2 gene, is characterized by growth delay, intellectual disability, abnormal behaviors, and craniofacial and skeletal anomalies." (PMID 30809123, 2019). "The human SATB2 locus is highly constrained, rare mutations in the gene cause intellectual disability, and the gene influences cognitive ability in the general population." (PMID 30726206, 2019). "SATB2-associated syndrome (SAS) results from various mutations of the SATB2 gene and associates a neurodevelopmental disorder including major speech delay, intellectual disability, and behavioral problems with dental anomalies, sometimes a cleft palate, risk of osteoporosis, and facial dysmorphism." (PMID 40474278, 2025). "These SATB2 gene-sets were enriched for genes containing common variants associated with schizophrenia and EA, and were enriched for genes containing rare variants reported in studies of schizophrenia, autism and intellectual disability." (PMID 30040823, 2018). "De novo structural and point mutations in SATB2 result in SATB2 haploinsufficiency and SATB2-associated syndrome, which is characterised by developmental delay, mild to severe intellectual disability, speech and behavioural problems and abnormal craniofacial features." (PMID 30040823, 2018). "SATB2 haploinsufficiency is a common cause of syndromic intellectual disability." (PMID 28151491, 2017). "In a case report, the mutation of special AT-rich special sequence-binding protein 2 (SATB2) which encoded a DNA-binding protein can lead to severe intellectual disabilities in children, suggesting that SATB2 may play a disadvantageous role in nervous development." (PMID 34621711, 2021). "For instance, the ASD risk gene SATB2 is evolutionarily conserved and encodes a DNA-binding protein involved in transcriptional regulation and chromatin remodeling, and mutations in SATB2 have been reported to be associated with cleft palate, facial dysmorphism and intellectual disability." (PMID 33160303, 2020). "Mutations in the SATB2 gene lead to SATB2-associated syndrome (SAS), characterized by severe intellectual disability." (PMID 42091597, 2026). "In humans, mutations of SATB2 cause SATB2 Associated Syndrome (SAS), a multisymptomatic syndrome involving epilepsy, intellectual disability, speech delay, and craniofacial defects." (PMID 39152101, 2024). "Next, we tested the human SATB2 interactor gene-sets (adult and neonatal) for enrichment of highly constrained genes and intellectual disability (ID) genes." (PMID 30726206, 2019). "Several potentially pathologic genes within the deleted region were of interest including the intellectual disability gene SATB2 and the CD28/CTLA4/ICOS immune gene cluster." (PMID 30087679, 2018). "SATB2 also likely influences brain development, as illustrated by the severe mental retardation seen in these subjects." (PMID 19668335, 2009).
Intellectual disability (continued). "Common variation in SATB2 locus confers risk of schizophrenia, whereas rare, de novo structural and single nucleotide variants cause severe intellectual disability and absent or limited speech." (PMID 30726206, 2019). "In humans patients, alterations of the SATB2 gene (de novo structural or single nucleotide variants) cause developmental delay, intellectual disability, limited to absent speech and behavioral issues." (PMID 30726206, 2019). "SATB2 is reduced/absent in some individuals manifesting developmental delay, intellectual disability, and severe speech delay — common alterations in patients with AHDS." (PMID 38376950, 2024). "Given the highly specific expression pattern of Satb2 in the adult brain as well as the severe learning disabilities and mental retardation observed in SAS patients, we hypothesized that Satb2 is critical for learning and memory." (PMID 27897969, 2016).
osteoporosis (20 papers, 2016 to 2025). A condition of reduced bone mass, with decreased cortical thickness and a decrease in the number and size of the trabeculae of cancellous bone (but normal chemical composition), resulting in increased fracture incidence. "We conclude that SATB2 pathogenic variants are responsible for skeletal demineralization and osteoporosis." (PMID 35241104, 2022). "Further investigations into the mechanisms of SATB2 loss with aging in bone are warranted to expand our knowledge on BMSCs senescence as well as osteoporosis." (PMID 27632702, 2016). "In a mouse model of osteoporosis, BM‐MSC‐EVs that contain MALAT1 enhance osteoblast activity by regulating the miR‐34c/SATB2 axis, thereby alleviating osteoporosis." (PMID 40290901, 2025). "After mechanistic research, they recognized that miR-483-5p contributed to the pathogenesis of osteoporosis by inhibiting SATB2 and activating the PI3K/AKT pathway." (PMID 37251576, 2023). "qRT-PCR results revealed that the miR-483-5p expression level was greater and that of SATB2 was lower in patients with osteoporosis compared to the control." (PMID 33621956, 2021). "It is interesting to note that miR‐34s serve as an inhibitor in osteoblast proliferation by decreasing levels of Cyclin D1, CDk4, and CDK6 and a suppressor in osteoblast differentiation by decreasing SATB2 to facilitate the progression of osteoporosis." (PMID 33434305, 2021). "In summary, our current study illustrated that miR-483-5p is up-regulated in postmenopausal osteoporosis and affects the osteoporosis progression by targeting SATB2 and activating the PI3K/AKT signaling pathway." (PMID 33621956, 2021). "Aberrant regulation of SATB2 is closely related to several types of diseases, including cancer, Parkinson's disease, and osteoporosis." (PMID 33621956, 2021). "The miR-483-5p mimic significantly inhibited the SATB2 expression, while SATB2 overexpression successfully reversed the progress of osteoporosis induced by miR-483-5p." (PMID 33621956, 2021). "Previous results have shown that oestrogen regulates osteogenic differentiation of BMSCs via the ERβ-SATB2 pathway to prevent osteoporosis." (PMID 32420385, 2020). "Another team also proved that lncRNA-MALAT1 acts as a sponge of miR-34c to increase the expression of special AT-rich sequence binding protein 2 (SATB2), which is conducive to restoring osteogenesis in osteoporosis conditions." (PMID 32963550, 2020). "ERβ is protective for bone loss and estrogen was shown to regulate bone marrow stromal cells senescence and stemness to prevent osteoporosis via ERβ and special AT-rich sequence binding protein 2 (SATB2) transcription factor." (PMID 30337927, 2018). "Furthermore, Xucheng Yang confirmed that lncRNA malat-1 shuttled by EVs derived from bone marrow mesenchymal stem cells-secreted EVs alleviates osteoporosis through mediating microRNA-34c/SATB2 axis." (PMID 34976968, 2021). "As expected, SATB2 overexpression apparently inhibited the osteoporosis progression." (PMID 33621956, 2021). "For instance, increased SATB2 has been confirmed to promote osteogenic differentiation during the progression of osteonecrosis; thus, upregulation of SATB2 has been reported to promote the progression of osteoporosis." (PMID 34043680, 2021). "We could not determine miR-103 expression and the correlation between miR-103 and SATB2 in osteoporosis patients." (PMID 32379794, 2020). "Taken together, the results suggest that oe-MALAT1, oe-SATB2 or si-miRNA-34c could help prevent osteoporosis in OVX mice." (PMID 31659145, 2019). "In summary, our study provides evidence that BMSCs-derived exosomal MALAT1 may contribute to enhanced osteogenic activity and alleviated symptoms of osteoporosis in the mouse model by acting as a miR-34c sponge to upregulate SATB2 expression." (PMID 31659145, 2019). "Moreover, evidence has been presented indicating that SATB2 is closely correlated with the function of BMSCs, osteogenic activity and osteoporosis." (PMID 31659145, 2019).
osteoporosis (continued). "Defects or haploinsufficiency of SATB2 in humans is a clinically recognizable syndrome characterized by intellectual disability, craniofacial abnormalities, dysmorphic features, cleft palate, micrognathia, and osteoporosis." (PMID 27632702, 2016). "Interestingly, emerging evidence suggests that miR-483-5p may be involved in the pathogenesis of osteoporosis, and it has been proposed that the miR-483-5p/SATB2 axis could influence osteogenic differentiation and PI3K/AKT signaling." (PMID 41244896, 2025). "Besides, Pearson correlation test unveiled a significant negative association between miR-483-5p and SATB2 in both osteoporosis and control patients, suggesting the participation of miR-483-5p and SATB2 for the osteoporosis occurrence." (PMID 33621956, 2021). "Since SATB2, ATF4 and Runx3 are three key mediators of osteoporosis, western blot analysis was used to detect the expression levels of their proteins." (PMID 34043680, 2021). "Special AT-rich sequence-binding protein 2 (SATB2) is a stemness and senescence regulator, which can regulate the progression of osteoporosis." (PMID 34043680, 2021). "Although the role of SATB2 in pathological states such as osteoporosis and diabetes mellitus has not yet been validated, the present study provides a theoretical basis for SATB2 in the clinical treatment of fractures." (PMID 40822968, 2025). "Interestingly, there was increasing evidence that miR-483-5p was involved in the pathogenesis of osteoporosis, and osteogenic differentiation and PI3K/AKT signaling were also regulated by the miR-483-5p/SATB2 axis." (PMID 35300408, 2022). "The effects of miR-483-5p and SATB2 on osteoporosis were investigated by comparing their expression levels in postmenopausal patients with and without osteoporosis." (PMID 33621956, 2021).
cleft palate (15 papers, 2009 to 2025). Cleft palate is a fissure type embryopathy that affects the soft and hard palate to varying degrees. "Satb2 was first identified as a gene responsible for cleft palate and Satb2 mutation in mice leads to perinatal death and severe craniofacial defects." (PMID 40164579, 2025). "Heterozygous loss-of-function (LOF) mutations in the gene encoding the DNA-binding protein, SATB2, result in micrognathia and cleft palate in both humans and mice." (PMID 24363063, 2014). "Haploinsufficiency of the SATB2 gene is the most likely cause of cleft palate in these translocation patients." (PMID 23840981, 2013). "Although haploinsufficiency of SATB2 has been suggested to cause isolated cleft palate in humans, within our cohort SATB2 deletions show reduced penetrance for cleft palate." (PMID 19668335, 2009). "A single case of a de novo nonsense mutation of SATB2 has been described in an individual with cleft palate, osteoporosis, profound mental retardation, epilepsy, a jovial personality, and craniofacial dysmorphism including gum hyperplasia, mandibular hypoplasia, and anterior-pointing incisors." (PMID 19668335, 2009). "We recommend close monitoring of prelanguage communication in infants with apparently isolated cleft palate or RS and the search for SATB2 impairment when a cleft palate or RS is found, especially in the prenatal period." (PMID 40474278, 2025). "For instance, DECIPHER reports SATB2 to be linked to simply ‘cleft palate’, whereas in OMIM the gene is mapped to Glass syndrome, for which one of the hallmarks is cleft palate." (PMID 33836063, 2021). "Given the combination of cleft palate and micrognathia in SATB2 haploinsufficiency cases, there is a clear overlap with the spectrum of craniofacial malformations seen in genetically characterized forms of PRS." (PMID 24363063, 2014). "Incomplete penetrance has been observed in mouse models; one study of Satb2-haploinsufficient mice showed cleft palate in approximately 25%, whereas another population was reported as phenotypically normal." (PMID 19668335, 2009). "Given the high concordance of cleft palate and micrognathia in the affected individuals, we hypothesized that SATB2 may be a target of the transcription factor SOX9 as CRMs affecting SOX9 are a significant cause of PRS." (PMID 24363063, 2014). "A non-redundant role for SATB2 in craniofacial development was confirmed when targeted inactivation of the gene in mouse embryos was shown to result in severe midline facial malformations in homozygous embryos with cleft palate also occurring in heterozygotes at lower penetrance." (PMID 24363063, 2014). "Thus, SATB2 haploinsufficiency alone may not be sufficient for cleft palate; other factors, environmental or genetic, may need to be present to lead to clefting." (PMID 19668335, 2009).